FFAR2 (free fatty acid receptor 2)
Diseases named in the same sentence as FFAR2 in open-access papers (continued):
Sharing a sentence is not in itself a finding about the gene and the disease.
metabolic syndrome (15 papers, 2014 to 2025). A cluster of metabolic risk factors for CARDIOVASCULAR DISEASES and TYPE 2 DIABETES MELLITUS. "This indicates that incretin hormonal synthesis is associated with FFAR2/3 receptor signaling in response to metabolic syndrome in either direction." (PMID 32521775, 2020). "Therefore, in both humans and mice, SCFAs are associated with activation of FFAR2 in regulating biological functions such as incretin hormonal synthesis, metabolic syndrome, and occurrence of autoimmune diseases in host." (PMID 32521775, 2020). "As a result, SCFAs and FFAR-2 activation work together to control the onset of autoimmune diseases and the metabolic syndrome in both animal and human models." (PMID 36769034, 2023). "Therefore, in human and animal models, SCFAs are concomitant with FFAR-2 activation in regulating biological functions, such as hormonal synthesis, metabolic syndrome, and autoimmune disease occurrence." (PMID 35246012, 2022). "Furthermore, we hypothesized that increased FFAR2 and reduced FFAR4 expression in AT of type 2 diabetes patients associate with parameters of dyslipidemia." (PMID 30190473, 2018).
Hyperglycemia (13 papers, 2016 to 2025). An increased concentration of glucose in the blood. "Loss of Ffar2 in mice increases the risk of diabetic status, since Ffar2 knockout (KO) mice exhibit fasting hyperglycemia, reduced insulin levels, and glucose intolerance, despite exhibiting normal insulin sensitivity." (PMID 32404878, 2020). "We identified that the proportion of A. muciniphila and the expression of Ffar2, were significantly increased with improved hyperglycemia at 5 mpi." (PMID 39429872, 2024). "Therefore, we first explore if maternal hyperglycemia during pregnancy due to Ffar2 deletion is sufficient to lead to aberrant metabolic health in their offspring." (PMID 27959892, 2016). "FFAR3 activation, similar to FFAR2, stimulates GLP-1 secretion, thereby preventing hyperglycemia." (PMID 33897464, 2021). "FFAR2 stimulates enteroendocrine L cell GLP-1 secretion and prevents hyperglycemia." (PMID 33897464, 2021). "It is also possible that the degree of maternal hyperglycemia in Ffar2-/- mice is not sufficient to induce acute metabolic effects on the offspring, as the degree of impairment in the LIRKO mice is more severe than that of the Ffar2-/- mice during pregnancy." (PMID 27959892, 2016).
breast carcinoma (12 papers, 2017 to 2026). "FFAR2 and FFAR3 act as tumor suppressors in colon and breast cancer; the loss of FFAR2 promotes colon tumorigenesis." (PMID 35785152, 2022). "In addition, inhibition of Hippo/YAP signaling, upregulation of E-cadherin expression, and prevention of the formation of the invasive phenotype of cancer cells were caused by SCFAs binding to FFAR2 on the surface of breast cancer cells." (PMID 38699473, 2024). "The presence of FFAR2 was first demonstrated in a human breast cancer cell line and its activation by propionate increased intracellular calcium and the phosphorylation of mitogen-activated protein kinase (MAPK) p38." (PMID 33113952, 2020). "Strikingly, we discovered the lowest levels of FFAR2 expression in breast cancer, prostate cancer and hematological diseases especially in leukemia." (PMID 32517300, 2020). "This led us to investigate the mechanisms underlying FFAR2- and FFAR3-mediated effects on breast cancer cells, particularly pertaining to metastasis." (PMID 29049318, 2017). "In a similar manner to that described for FFAR2, the expression of FFAR3 was early detected in a human breast cancer line, and contradictory results have been reported about its expression in human cancer and its role in carcinogenesis." (PMID 33113952, 2020). "As studies suggest that FFAR2 expression is reduced in certain cancers, and that proliferation may be inhibited by short chain fatty acids, butyrate and propionate, we speculated that short chain fatty acid receptors might play a role in regulating breast cancer progression, and possibly metastasis." (PMID 29049318, 2017). "To understand the functions of FFAR2 and FFAR3 in breast cancer metastasis, we evaluated two breast cancer cell lines that have contrasting EMT phenotypes reflected by their EMT score: 1.0 = highly mesenchymal, -1.0 = highly epithelial." (PMID 29049318, 2017). "Since our data suggest that FFAR2 and FFAR3 inhibit EMT, we speculated that expression of these receptors is likely to be reduced in invasive breast cancer tissues." (PMID 29049318, 2017). "Furthermore, to corroborate the involvement of FFAR2 in the regulation of E-cadherin expression, we evaluated the correlation between FFAR2 and CDH1 mRNA levels in breast tumors and breast cancer cell lines." (PMID 29049318, 2017).
diabetic nephropathy (12 papers, 2020 to 2025). "Studies indicated that SCFAs could activate free fatty acid receptor 2 (FFAR2, also called GPR43) and protein kinase B (PKB, more often called AKT) signaling to improve muscular atrophy in mice of diabetic nephropathy model." (PMID 39831118, 2024).
Sepsis (12 papers, 2015 to 2025). Sepsis is defined as life-threatening organ dysfunction caused by a dysregulated host response to infection. "To investigate the involvement of these receptors in the protective effects of SCFAs against sepsis-associated arrhythmia, we measured the levels of FFAR2 and FFAR3 using western blot." (PMID 39228788, 2024). "From a mechanistic perspective, the therapeutic effect of SCFAs in treating arrhythmias caused by sepsis is attributed to their antibacterial effect against C. sakazakii, but the involvement of SCFAs-related receptors, such as FFAR2 and FFAR3, also plays an important role." (PMID 39228788, 2024). "Nevertheless, for life-threatening infections such as severe sepsis, transient FFAR2 manipulation could represent a novel therapeutic strategy for boosting immune reactions and improving the outcome of infectious diseases." (PMID 34926327, 2021). "Tier 2 sepGIKs included 89 sepGIKs (399 pairs), such as FFAR2 (free fatty acid receptor 2), CCR7 (C-C chemokine receptor type 7), HK3 (hexokinase 3), and IRAK3 (interleukin-1 receptor-associated kinase 3), which were differentially expressed in at least 14 sepsis datasets." (PMID 40761792, 2025). "Collectively, FFAR2, MAPK14, LTB, SAMD9L shown dysregulation in all three studies, indicating their roles at both cellular and system-level responses to sepsis." (PMID 30086151, 2018). "In general, FFAR2 exhibits anti-inflammatory and antioxidant stress effects in ALI, and the expression of FFAR2 is related to the increase of 30-day survival in patients with sepsis." (PMID 38456906, 2024). "We found that blocking FFAR2 by GLPG0974 abolished the anti-arrhythmic and sepsis-protective effects of SCFAs, C2, and C4, indicating that the anti-arrhythmic effect of SCFAs in sepsis is partly dependent on FFAR2." (PMID 39228788, 2024). "This priming improved the capacity of human neutrophils to eliminate methicillin-resistant S. aureus (MRSA) and rescued wild-type but not FFAR2-/- mice from severe S. aureus sepsis." (PMID 34926327, 2021).
colorectal cancer (11 papers, 2020 to 2025). A primary or metastatic malignant neoplasm that affects the colon or rectum. "Previous studies of SCFAs/FFAR2 signaling are most focused on gut microbiota mediated immune regulation colorectal cancer model." (PMID 38402237, 2024). "For instance, various studies have shown that the decreased expression of FFAR2 in CRC tissues and various colorectal cancer cell lines, which may indicate the role of FFAR2 in disease development or progression." (PMID 37175726, 2023).
Hepatic steatosis (11 papers, 2015 to 2026). Steatosis is a term used to denote lipid accumulation within hepatocytes. "Acetate produced by the gut microbiota inhibits the progression of fatty liver disease through the hepatic FFAR2 signaling pathway." (PMID 38192650, 2023). "Furthermore, modulation of nuclear receptors such as AHR, FFAR2, FXR, and TGR5 links metabolic-associated fatty liver disease, COVID-19, and oxidative stress." (PMID 41415278, 2025). "This study investigated the messenger RNA (mRNA) expression levels of four genes (AHR, FFAR2, FXR, and TGR5) in patients with COVID-19, stratified by the presence or absence of metabolic-associated fatty liver disease (MAFLD)." (PMID 38932276, 2024). "However, the authors concluded that sodium butyrate may prevent fatty liver disease progression via histone deacetylase rather than FFAR2 as GLP-1 receptor expression was unaffected by FFAR2 siRNA in vitro." (PMID 33897464, 2021).
gout (10 papers, 2016 to 2024). A condition characterized by painful swelling of the joints, which is caused by deposition of urate crystals. "This ligand–receptor interaction may represent a key signal for the development of inflammatory response in gout as FFAR2-deficient mice (GPR43–/–) showed reduced neutrophil recruitment and poor assembly of the inflammasome upon injection with MSU crystals compared with the wild type." (PMID 35731142, 2023). "FFAR2 upregulation is associated with gout and may trigger gout flares." (PMID 35731142, 2023). "FFAR2 was also significantly upregulated during inter-critical gout (FC = 1.8) compared with normal SU, AH and AH + MSU (FC = 1.1, P < 0.001 for each comparison)." (PMID 35731142, 2023). "FFAR2 was significantly upregulated during gout flares (FC = 2.9) compared with normal SU, AH, and AH + MSU crystal deposition (FC = 1.1, P < 0.0001 for each comparison)." (PMID 35731142, 2023). "FFAR2 expression was upregulated during gout flare compared with inter-critical gout and SOCS3 expression showed negative correlation with flare duration (r = –0.49, P < 0.05)." (PMID 35731142, 2023). "FFAR2 gene expression was increased in inter-critical gout and increased further during a gout flare." (PMID 35731142, 2023). "FFAR2 expression was increased during inter-critical gout compared with normal SU, AH and AH + MSU crystal deposition." (PMID 35731142, 2023). "A previous study has demonstrated that acetate acid mediated joint inflammation in a murine gout model through inflammasome assembly and IL-1β production that is partially FFAR2 dependent." (PMID 35684581, 2022). "Additionally, FFAR2 KO mice reveal decrease in adaptive inflammatory response as compare to WT littermate in gout pathology." (PMID 32521775, 2020). "Therefore, an involvement of FFAR2 activation necessary for the onset of the inflammatory response of gout could be explained by the same mechanism." (PMID 35731142, 2023). "In conclusion, we have reported on the expression of FFAR2 and SOCS3 in the PBMCs of people with pre-clinical and symptomatic phases in the gout hyperuricemia spectrum." (PMID 35731142, 2023). "This study reported on the expression of FFAR2 and SOCS3 genes in PBMCs during different pre-clinical, and clinical states in the gout hyperuricemia spectrum." (PMID 35731142, 2023). "Additionally, FFAR2 expression was significantly increased during gout flares compared with inter-critical gout, and SOCS3 gene expression was significantly increased early during gout flares." (PMID 35731142, 2023). "Therefore, the objectives of this study were to examine the expression of FFAR2 and SOCS3 genes in people with normal serum urate (SU), asymptomatic hyperuricemia (AH), AH with asymptomatic MSU crystal deposition (AH + MSU), inter-critical gout and gout flare." (PMID 35731142, 2023).
inflammatory bowel disease (10 papers, 2012 to 2024). A spectrum of small and large bowel inflammatory diseases of unknown etiology. "Diversion colitis and inflammatory bowel disease (IBD) are two diseases associated with FFAR2." (PMID 37817005, 2024). "A decrease in the concentration of SCFAs such as butyrate, propionate and acetate reduces the number of Treg in the gut upsetting the Th17/Treg balance, and the level of mRNA FFAR2 changes with the development of experimental inflammatory bowel disease (IBD)." (PMID 32685120, 2020). "Indeed FFAR2 holds promise for the management of Inflammatory Bowel Disease (IBD) a possible side-effect of anti-diabetic treatment with DPP-IV inhibitors." (PMID 30364192, 2018).
Glucose intolerance (9 papers, 2020 to 2025). Glucose intolerance (GI) can be defined as dysglycemia that comprises both prediabetes and diabetes. "Mice with global deletion of FFAR2 exhibited fasting hyperglycemia and glucose intolerance after HFD feeding, resulting from a defect in beta cell function and mass." (PMID 37484954, 2023). "In the oral glucose tolerance test, the blood glucose profiles of WT and Ffar2−/− mice fed the HFC diet were similar, indicating that FFAR2 deficiency did not alter the severity of glucose intolerance." (PMID 34530928, 2021).
Crohn disease (8 papers, 2012 to 2025). A gastrointestinal disorder characterized by chronic inflammation involving all layers of the intestinal wall, noncaseating granulomas affecting the intestinal wall and regional lymph nodes, and transmural fibrosis. "We investigated the expression of GPR43/FFAR2 in the colon from Crohn’s disease patients and whether dietary fiber in enteral nutrition increases GPR43+ polymorphonuclear infiltration in mucosa." (PMID 26140540, 2015). "We sought to investigate the expression of GPR43/FFAR2 in the colon of CD patients to deduce whether this expression in enteroendocrine cells is the same as that in non-Crohn’s disease patients." (PMID 26140540, 2015).
depression (6 papers, 2020 to 2025). "This suggests that upregulation of the ACE/FFAR2 pathway is a key mechanism for targeting microbes in the treatment of depression accompanied by constipation." (PMID 41278468, 2025). "However, the potential of SCFAs to inhibit microglial activation via FFAR2 and suppress neuroinflammation for depression treatment remains to be explored." (PMID 41278468, 2025). "In summary, we suggest that LQYY may achieve the purpose of treating depression and constipation by increasing ACE and FFAR2, inhibiting neuroinflammation and increasing colonic 5-HT expression." (PMID 41278468, 2025).
leukemia (6 papers, 2018 to 2022). A malignant (clonal) hematologic disorder, involving hematopoietic stem cells and characterized by the presence of primitive or atypical myeloid or lymphoid cells in the bone marrow and the blood. "Recently, a FFAR2 agonist with favorable pharmacokinetic properties has been developed allowing the targeting of FFAR2 as a new therapeutic strategy in KMT2Ar leukemia." (PMID 32517300, 2020). "It has been demonstrated that downregulation of FFAR2 is necessary for leukemia survival in vitro and in vivo." (PMID 32517300, 2020). "By re-analyzing publicly available datasets, we were able to assign FFAR2 an important role in leukemia by demonstrating a significant downregulation in leukemic patients in contrast to different other tumor entities and healthy controls." (PMID 32517300, 2020). "This could be further confirmed by analyzing leukemia patient data of different entities, again showing very low levels of FFAR2 in contrast to healthy controls." (PMID 32517300, 2020). "Downregulation of FFAR2 seems to be mandatory for leukemia development and therefore could serve as therapeutic target in the treatment of poor prognosis KMT2Ar leukemia." (PMID 32517300, 2020). "Until now, the impact of FFAR2 is only poorly understood in leukemia." (PMID 32517300, 2020).
viral infection (6 papers, 2015 to 2025). "Further experiments showed that inhibition of GPR43 (free fatty acid receptor 2) in intestinal epithelial cells increased virus infection and reduced antiviral effects through IFN λ response." (PMID 36744090, 2023). "In contrast to wild-type A549 cells, acetate pre-treatment in FFAR2-deficient cells had no impact on viral load, clearly indicating that FFAR2 is essential for mediating the acetate-induced reduction in viral infection." (PMID 40745568, 2025). "To test the impact of GPR41 and GPR43 on CD8+ T cell priming following viral infection, we infected C57BL/6 wildtype (WT) mice and mice lacking GPR41 and GPR43 (Ffar2–/–;Ffar3–/–) epicutaneously with HSV-1 and examined the endogenous HSV-specific CD8+ T cell response using H2-Kb-gB498-505 tetramers." (PMID 38524121, 2024).
atherosclerosis (5 papers, 2012 to 2023). A disease characterized by the build-up of fatty material and calcium deposition in the arterial wall resulting in partial or complete occlusion of the arterial lumen. "Several of the differentially regulated genes are involved in vascular pathophysiology; for example: DNAJB6 and DUSP1 (atherosclerosis), NAMPT (vascular inflammation), FCAR (myocardial infarction), IL8 (vascular remodelling), FFAR2 (lipid metabolism) and SOD2 (idiopathic cardiomyopathy (IDC))." (PMID 22409835, 2012).
Autoimmunity (5 papers, 2019 to 2024). The occurrence of an immune reaction against the organism's own cells or tissues. "This study delineates the importance of Ffar2 signaling in colonic T cells for counteracting CNS autoimmunity." (PMID 38238790, 2024). "Specifically, our results indicate that Ffar2-mediated modulation of the immune properties of intestinal ILC3 during the induction of EAE effectively ameliorates CNS autoimmunity with clinical benefit on disease progression." (PMID 38238790, 2024). "The importance of stimulation of ILC3 for autoimmunity prevention or treatment resides in their FFAR2-mediated IL-22 production and proliferation, but also in the fact that this FFAR2-mediated stimulation will not initiate IFN-γ production." (PMID 34149694, 2021).
Chronic colitis (5 papers, 2017 to 2024). A chronic inflammatory disease of the large intestine (colon, cecum and rectum). "The disparate results for FFAR2 in the chronic colitis model may stem from differences in the respective experimental setups involving different timings for the sequences of DSS administration as well as different concentrations of DSS." (PMID 33578942, 2021).
Impaired glucose tolerance (5 papers, 2015 to 2019). An abnormal resistance to glucose, i.e., a reduction in the ability to maintain glucose levels in the blood stream within normal limits following oral or intravenous administration of glucose. "To determine the impact of impaired glucose tolerance on the early life of offspring in this model, we further bred WT x WT, Ffar2+/- x Ffar2+/- and Ffar2-/- x Ffar2-/- breeding pairs and we compared the litter size and survival rates of their offspring." (PMID 27959892, 2016). "Because of the known influence of elevated glucose levels on fetal health, we examined if the impaired glucose tolerance in our female Ffar2-/- mice during pregnancy influenced the metabolic fitness of their offspring." (PMID 27959892, 2016). "Because the Ffar2+/- female mice do not develop impaired glucose tolerance, this allows us to assess the influence of impaired maternal glucose tolerance on the metabolic health of the Ffar2-/- offspring." (PMID 27959892, 2016).